NPSR1 (neuropeptide S receptor 1)
Description:
G protein-coupled receptor for neuropeptide S (NPS). Receptor activation by NPS initiates a G(q)/GNAQ-dependent phospholipase C-activating signaling pathway, resulting in Ca(2+) mobilization from intracellular stores and increased intracellular Ca(2+) levels. In addition to this pathway, NPS binding to its receptor activates cAMP/PKA signal transduction. Finally, both pathways converge to activate ERK1/ERK2 phosphorylation and signaling cascade. Inhibits cell growth in response to NPS binding.
Synonyms: GPR154; GPRA; PGR14; ASRT2; FNSS3; NPSR; VRR1
Tractability: Small molecule: a high-quality ligand is known; it belongs to a druggable protein family. Antibody: UniProt places it where antibodies can reach, with high confidence; its Gene Ontology location is reachable by antibodies, with high confidence; UniProt predicts a signal peptide or a membrane-spanning region. PROTAC: a small molecule that binds it is known.
Target class: Peptide receptor (family A GPCR); Family A G protein-coupled receptor; Short peptide receptor (family A GPCR); Membrane receptor; Neuropeptide receptor
Chemical probes: ML079, ML154 (high quality), QA1
Gene: Protein-coding gene on chromosome 7 (34,658,218 to 34,878,332, forward strand). Ensembl gene ENSG00000187258.
Subcellular location: Cell membrane (Isoform 1); Cell membrane (Isoform 3); Cell membrane (Isoform 4); Cytoplasm (Isoform 2); Cytoplasm (Isoform 5); Cytoplasm (Isoform 6); Cytoplasm (Isoform 7); Cytoplasm (Isoform 9)
Pathways (Reactome):
Signal Transduction: G alpha (q) signalling events; G alpha (s) signalling events; Peptide ligand-binding receptors
Gene Ontology:
Molecular function: neuropeptide receptor activity; protein binding; G protein-coupled receptor activity; vasopressin receptor activity
Biological process: phospholipase C-activating G protein-coupled receptor signaling pathway; positive regulation of cAMP/PKA signal transduction; positive regulation of ERK1 and ERK2 cascade; positive regulation of release of sequestered calcium ion into cytosol; eating behavior; G protein-coupled receptor signaling pathway; negative regulation of defecation; negative regulation of eating behavior; neuropeptide signaling pathway; righting reflex
Cellular component: cytoplasm; plasma membrane; membrane
Genetic constraint (gnomAD): Loss-of-function variants: 34 observed, 32.13 expected, observed/expected ratio (o/e) 1.06, 90% interval 0.8 to 1.41. The upper end of that interval is the gene's LOEUF score, 1.41, which puts it in group 5 of 6, group 1 being the genes least tolerant of losing a copy. Missense variants: 354 observed, 370.59 expected, observed/expected ratio (o/e) 0.96, 90% interval 0.88 to 1.04. Synonymous variants: 140 observed, 143.34 expected, observed/expected ratio (o/e) 0.98, 90% interval 0.85 to 1.12.
Homologues: Orthologues: macaque NPSR1 (97% identical), chimpanzee NPSR1 (92% identical), mouse Npsr1 (89% identical), rat Npsr1 (89% identical), dog NPSR1 (88% identical), pig NPSR1 (88% identical), rabbit NPSR1 (88% identical), guinea pig NPSR1 (84% identical), tropical clawed frog npsr1 (68% identical), zebrafish si:dkey-78k11.9 (20% identical).
Diseases named in the same sentence as NPSR1 in open-access papers:
NPSR1 is named in the same sentence as 61 diseases in open-access papers, as found by Europe PMC text mining. Sharing a sentence is not in itself a finding about the gene and the disease. The quoted sentences say what the papers report.
asthma (43 papers, 2005 to 2026). "ABCA7 gene expression is associated with nocturnal asthma symptoms in individuals with a polymorphism in NPSR1." (PMID 38540988, 2024). "PLAGL1 is associated with transient neonatal diabetes mellitus and paternal uniparental disomy of chromosome 6, and NPSR1 is associated with asthma-related traits." (PMID 38291454, 2024). "For example, a single-nucleotide polymorphism of NPSR1 is significantly associated with disease, such as asthma, anxiety and panic disorder, and rheumatoid arthritis." (PMID 34069327, 2021). "The region on human chromosome 7 harboring NPSR1 was first identified in a positional cloning approach to contain an asthma-susceptibility gene." (PMID 33922620, 2021). "NPSR1 is a G protein-coupled receptor that has been linked to asthma susceptibility and inflammatory bowel disease." (PMID 29967566, 2018). "We sought to examine the effects of different combinations of these NPS and NPSR1 variants on downstream signaling and genetic risk of asthma." (PMID 28463995, 2017). "In conclusion, NPS variants modify asthma risk and should be considered in genetic association studies of NPSR1 with asthma and other complex diseases." (PMID 28463995, 2017). "In conclusion, our results supported the association of the NPS/NPSR1 pathway with asthma and provided a molecular framework on how the different NPS and NPSR1 variants interact in asthma." (PMID 28463995, 2017). "NPSR1 was identified as a susceptibility gene for asthma and related traits by positional cloning and has been replicated in several independent association studies, and marginally supported by GWAS." (PMID 23565190, 2013). "Since both RORA and NPSR1 are independently associated with asthma, we evaluated the potential epistasis between polymorphisms in these genes (‘gene-gene interactions’)." (PMID 23565190, 2013). "Neuropeptide S Receptor 1 (NPSR1) has been associated with asthma and allergy and a study suggested modulation of the genetic risk by environmental factors." (PMID 23372674, 2013). "The Neuropeptide S Receptor 1 (NPSR1) gene on chromosome 7p14.3 encodes a G-protein coupled receptor that has been associated to many complex disorders such as asthma, irritable bowel syndrome, rheumatoid arthritis and psychiatric disorders." (PMID 23372674, 2013). "In summary, DNA methylation levels in the promoter of NPSR1 showed small but significant associations with asthma, both in adults and in children, and to related traits such as allergy and certain environmental exposures." (PMID 23372674, 2013). "It has been recently shown that methylation levels in the promoter of Neuropeptide S Receptor 1 (NPSR1) gene were associated to asthma in both children and adults as a result of smoking exposure." (PMID 23641254, 2013). "Similar results were observed for RORA SNP rs8024629 and RORA SNP rs9302215 which only increase the risk of asthma in individuals carrying the functional haplotype CAC in NPSR1 (rs2530547C/rs324981A/rs727162C)." (PMID 23565190, 2013). "Previous studies have reported significant associations for a large region of 47 kb in the NPSR1 gene with asthma even after Bonferroni correction for multiple comparisons (P<0.001)." (PMID 23663310, 2013). "Since the present study strongly indicates an association with genetic variation in the NPSR1 gene also in AR, there is an obvious risk of asthma being a cxonfounding factor for our results." (PMID 23663310, 2013). "To date, the association of NPSR1 to asthma and allergy has been replicated in seven independent populations." (PMID 21707994, 2011). "The increasing number of positive association studies supports the concept that NPSR1 is mechanistically involved in asthma and allergy, and also in other diseases." (PMID 21707994, 2011). "Polymorphism in the neuropeptide S receptor gene NPSR1 is associated with asthma and inflammatory bowel disease." (PMID 20179762, 2010).
asthma (continued). "We have previously shown that several susceptibility alleles of low-to-moderate-effects in NPSR1 may modify the asthma risk and show epistasis depending on the carrier status for variants in genes belonging to common biological pathways." (PMID 28463995, 2017). "For example, it is likely that an interaction between variant forms of NPSR1 with variants of the retinoid receptor-related orphan receptor alpha (RORA) nuclear repressor gene may contribute to a variety of asthma phenotypes." (PMID 27990118, 2016). "However, and interestingly, the NPSR1 gene was originally described as an asthma susceptibility gene, and significant SNP and haplotype associations of NPSR1 gene with asthma was established in several independent populations." (PMID 26441556, 2015). "Many of the genetic associations concerning NPSR1 and asthma are related to allergic asthma." (PMID 23372674, 2013). "Taken together, we showed that combinations of common susceptibility alleles (in RORA) and less common functional polymorphisms (in NPSR1) could modify the joint risk effect on asthma susceptibility." (PMID 23565190, 2013). "In summary, DNA methylation levels in the promoter of NPSR1 showed significant associations with asthma and related traits such as allergy, as well as with certain exposures, when measured in DNA from whole blood, although absolute differences were generally small." (PMID 23372674, 2013). "Furthermore, genetic variants together with environmental factors seemed to play a role for allergic diseases, such as the use of antibiotics early in life and COL29A1 variants for asthma, and farm living and NPSR1 variants for allergic eczema." (PMID 24260339, 2013). "Next, we investigated whether SNPs located in the predicted NPSR1 promoter region were associated with asthma and other obstructive airway disease in the 171 adult samples from BIOAIR and the 260 BAMSE children." (PMID 23372674, 2013). "Since NPSR1 is a strong candidate gene for asthma and one study suggested that its genetic risk is modulated by the environment, we aimed to study DNA methylation in the regulatory region of NPSR1 in relation to asthma and environmental exposures." (PMID 23372674, 2013). "The previous genetic associations seen to IgE levels and allergy in relation to asthma for NPSR1 polymorphisms, in combination with our results in this study, highlight the importance this gene might have in the corresponding biology." (PMID 23372674, 2013). "Furthermore, NPSR1 has not only been associated to asthma and related phenotypes but also to other diseases and target tissues." (PMID 23372674, 2013). "The importance of the NPS-NPSR1 signaling pathway is highlighted by the observation that, in humans, NPSR1 polymorphism associates with asthma, inflammatory bowel disease, rheumatoid arthritis, panic disorders, and intermediate phenotypes of functional gastrointestinal disorders." (PMID 22216302, 2011). "However, the association and mechanisms for how NPSR1 signals in other immune-mediated phenotypes such as asthma, psoriasis, and allergies as well as downstream signaling in inflammatory cascades that imply similar propensities may occur in UC." (PMID 29983891, 2018). "Notably, the association of RORA rs7164773 with asthma might depend on the convergence with rare alleles of the NPSR1 SNPs rs6972158 on chromosome 7." (PMID 23565190, 2013). "Thus, the association between variation in NPSR1 and asthma appear to be strongly supported." (PMID 23663310, 2013). "Some of the polymorphisms previously identified through GWAS for asthma and related phenotypes also showed suggestive associations in our GWAS samples, including the SNPs within previously known candidate regions such the HLA locus on chromosome 6 and the NPSR1 locus." (PMID 21625490, 2011).
asthma (continued). "While key causative polymorphisms await definitive identification through replication studies and functional characterization, this and previous findings strongly suggest that NPSR1 genetic variants may represent common risk factors for chronic inflammatory conditions such as RA, asthma and IBD." (PMID 20179762, 2010). "Increased expression of NPSR1 in eosinophils from patients with asthma or severe inflammation has been reported." (PMID 33922620, 2021). "NPSR1 was one of the candidate genes and was termed GPRA (G protein-coupled receptor for asthma susceptibility)." (PMID 33922620, 2021). "PTS exposure has also been related to lower promoter methylation in the neuropeptide S receptor 1 (NPSR1), significantly associated with asthma, and higher AXL gene methylation at birth, increasing bronchitic symptom risk in childhood." (PMID 32380770, 2020). "NPSR1, also called GPR154 or G-protein-coupled receptor for asthma susceptibility, codes for a 7-membrane receptor of unclear function and is likewise associated with susceptibility to inflammatory bowel disease and to neuroendocrine tumors." (PMID 29983891, 2018). "Neuropeptide S receptor 1 (NPSR1) was identified as a potential new drug target for asthma in the Open Targets platform." (PMID 30285606, 2018). "Altogether, our results supported the role of the NPS/NPSR1 pathway in asthma and the notion of a “combinatory effect”, in which the phenotype is driven by the interaction of several variants of moderate effects that coincide and affect a biological pathway." (PMID 28463995, 2017). "Both genetic variation and the methylated state of CpG sites seem to have an effect on the binding of nuclear proteins in the regulatory region of NPSR1 suggesting complex regulation of this gene in asthma and allergy." (PMID 23372674, 2013). "This study presents an extensive analysis of DNA methylation in the promoter of NPSR1 in relation to asthma, lifestyle and exposures in both adults and children." (PMID 23372674, 2013). "The results showed a small, but significantly lower NPSR1 promoter methylation level in children diagnosed with asthma ever up to age 8 as compared to healthy children at CpG site 4 (p = 0.04)." (PMID 23372674, 2013). "We aimed to study DNA methylation in the promoter region of NPSR1 in relation to asthma and environmental exposures." (PMID 23372674, 2013). "The RORA SNP rs8024629, only showed significant main effects for physician-diagnosed asthma by age 4 years, but it might also increase the risk for asthma in the combined dataset in the co-occurrence with the functional NPSR1 haplotype CAC (OR 2.63, 1.30–5.34; p = 0.007)." (PMID 23565190, 2013). "Several studies point towards an important role for NPSR1 in asthma and allergy, and moreover an explicit role for the -A and -B isoforms." (PMID 21707994, 2011). "Neuropeptide S receptor 1 (NPSR1 also GPRA, GPR154) was first identified as an asthma susceptibility gene through positional cloning." (PMID 21707994, 2011). "Neuropeptide S Receptor 1 (NPSR1, GPRA, GPR154) was first identified as an asthma candidate gene through positional cloning and has since been replicated as an asthma and allergy susceptibility gene in several independent association studies." (PMID 21707994, 2011). "Actually, the associations of ADAM33, NPSR1, and CYFIP2 with asthma or asthma-related phenotypes have been studied in Chinese or Japanese populations." (PMID 19951440, 2009). "For ADAM33, NPSR1, and CYFIP2, the associations with asthma or asthma-related phenotypes have been studied in East Asian populations such as Chinese and Japanese." (PMID 19951440, 2009). "STAT genes are present in several homologues in the genome, and in humans, defects, for example in STAT3 gene, have been connected with hyper‐IgE syndrome and atopic dermatitis and NPSR1 has been proposed to be involved in IgE‐mediated diseases in humans, such as allergic eczema and asthma." (PMID 33226152, 2021).
asthma (continued). "In the case of asthma, NPSR1 expression in eosinophils was observed." (PMID 34069327, 2021). "Despite strong human genetic data, the physiological role of NPSR1 in asthma, allergies, or inflammation remains unclear." (PMID 33922620, 2021). "Strong genetic evidence supports the hypothesis and the Open Targets platform identifies over 60 publications suggesting a role of NPSR1 in asthma but the exact mechanism of NPSR1 in the disease remains elusive." (PMID 30285606, 2018). "For example, Hamsten and colleagues recently drew attention to the differential expression of chemokine ligand 5 (CCL5), hematopoietic prostaglandin D synthase (HPGDS), and neuropeptide S receptor 1 (NPSR1) in the plasma of children with asthma using an antibody-based proteomic array." (PMID 27942431, 2016). "In candidate gene approaches, significant, albeit small differences in methylation of Neuropeptide S Receptor 1 (NPSR1) were observed in whole blood samples from adults with severe asthma and children with physician-diagnosed allergic asthma of a Swedish Birth cohort (BAMSE)." (PMID 26052354, 2015). "Moreover, the asthma candidate gene NPSR1 appeared in conjunction with the environment to predict allergic eczema outcomes." (PMID 24260339, 2013). "Based on the results indicating up-regulation of RORA mRNA expression after NPS stimulation of NPSR1 over-expressing cells, and the observation that NPSR1 is down-regulated by RORA, we studied the effects of gene-gene interaction between RORA and NPSR1 SNPs on the risk of asthma." (PMID 23565190, 2013). "Previous studies in PARSIFAL have shown that NPSR1 haplotypes are moderately associated with asthma and atopic sensitization, but not eczema." (PMID 24260339, 2013). "The present result indicates that NPSR1 could be a genetic link between AR and asthma and associations of NPSR1 polymorphisms with AR have not been reported prior to this." (PMID 23663310, 2013). "NPSR1 causative polymorphisms have not yet been conclusively identified and, although association with disease(s) has been replicated in different populations, there has not been always complete overlap of markers in previous associations with asthma and IBD." (PMID 20179762, 2010). "Six asthma candidate genes, ADAM33, NPSR1, PHF11, DPP10, HLA-G, and CYFIP2, located at different chromosome regions have been positionally cloned following the reported linkage studies." (PMID 19951440, 2009). "The results convincingly showed that asthma is no confounding factor for the SNPs in NPSR1 and CTLA4 in the Chinese population." (PMID 23663310, 2013). "Furthermore, NPSR1 knockout mice did not display asthma-related phenotypes or deficits in respiratory functions." (PMID 33922620, 2021). "No respiratory phenotypes were detected in NPSR1 knockout mice, including models of induced asthma." (PMID 33922620, 2021). "However, NPSR1 and CTLA4 can be genetic links between AR and asthma and associations of polymorphisms in NPSR1 with AR have not been reported previously." (PMID 23663310, 2013).